A1BG (alpha-1-B glycoprotein)
Synonyms: A1B; ABG; GAB; HYST2477
Tractability: Antibody: its Gene Ontology location is reachable by antibodies, with high confidence; UniProt places it where antibodies can reach, with medium confidence; UniProt predicts a signal peptide or a membrane-spanning region. PROTAC: its protein half-life has been measured.
Gene: Protein-coding gene on chromosome 19 (58,345,178 to 58,353,492, reverse strand). Ensembl gene ENSG00000121410.
Subcellular location: Secreted
Pathways (Reactome):
Hemostasis: Platelet degranulation
Immune System: Neutrophil degranulation
Gene Ontology:
Molecular function: transmembrane signaling receptor activity
Biological process: growth hormone receptor signaling pathway
Cellular component: blood microparticle; extracellular exosome; extracellular region; ficolin-1-rich granule lumen; plasma membrane; platelet alpha granule lumen; secretory granule lumen
Genetic constraint (gnomAD): Loss-of-function variants: 45 observed, 43.05 expected, observed/expected ratio (o/e) 1.05, 90% interval 0.82 to 1.34. The upper end of that interval is the gene's LOEUF score, 1.34, which puts it in group 5 of 6, group 1 being the genes least tolerant of losing a copy. Missense variants: 707 observed, 647.03 expected, observed/expected ratio (o/e) 1.09, 90% interval 1.03 to 1.16. Synonymous variants: 316 observed, 295.94 expected, observed/expected ratio (o/e) 1.07, 90% interval 0.97 to 1.17.
Homologues: Orthologues: chimpanzee A1BG (98% identical), macaque A1BG (90% identical), dog A1BG (66% identical), rabbit A1BG (61% identical), mouse A1bg (45% identical), rat A1bg (45% identical), rat A1bgl1 (41% identical), tropical clawed frog xilr1 (14% identical). Paralogues in human: LILRB3 (26% identical), LILRB1 (25% identical), LILRB5 (25% identical), LILRA4 (25% identical), LILRB2 (25% identical), LILRA1 (25% identical), LILRA6 (24% identical), LILRA2 (23% identical), IGSF1 (19% identical), KIR3DL3 (17% identical), LILRB4 (17% identical), KIR3DL1 (16% identical), and 13 more.
Diseases named in the same sentence as A1BG in open-access papers:
A1BG is named in the same sentence as 38 diseases in open-access papers, as found by Europe PMC text mining. Sharing a sentence is not in itself a finding about the gene and the disease. The quoted sentences say what the papers report.
breast carcinoma (8 papers, 2011 to 2023). "Finally, an independent validation showed FNDC1, A1BG, PDIA3, HSPA5, and calnexin as significant prognostic markers for human breast cancer patients." (PMID 34885011, 2021). "By analyzing heterogeneous intratumor subpopulations and metastatic sites, we demonstrated that FNDC1, A1BG, CANX, HSPA5, and PDIA3 may be key factors to tumor malignancy in a canine model of breast cancer." (PMID 34885011, 2021).
lung carcinoma (5 papers, 2012 to 2025). "Although A1BG has been reported to be overexpressed in plasma patients with type two diabetes mellitus, cervix, and lung cancers, its functional role is unknown and further needs to be investigated." (PMID 35818360, 2022). "We revealed that A1BG and LRG1 were overexpressed in both the blood level and tumor sections, which can be referred to separate lung cancer patients from healthy cases." (PMID 23284758, 2012). "Interestingly, A1BG and LRG1 were reported to be secreted by the A549 cell line and were found to be elevated in the serum of lung cancer patients." (PMID 26133466, 2015).
pancreatic ductal adenocarcinoma (4 papers, 2019 to 2024). An infiltrating adenocarcinoma that arises from the epithelial cells of the pancreas. "A1BG, another glycoprotein belonging to the immunoglobulin superfamily, was found overexpressed by proteomics in various forms of cancer, such as pancreatic ductal adenocarcinoma, cervical intraepithelial neoplasia and bladder cancer." (PMID 37046536, 2023). "A1BG, a member of the immunoglobulin superfamily, with unknown function, has been described to be elevated in pancreatic ductal adenocarcinoma and urinary samples from bladder cancer patients." (PMID 37089863, 2023).
bladder cancer (3 papers, 2011 to 2023). "Alpha-1 β glycoprotein (A1BG), a secreted protein of unknown function, was underexpressed in urines of bladder cancer patients." (PMID 21654678, 2011).
Obesity (3 papers, 2024 to 2025). Accumulation of substantial excess body fat. "A novel link between obesity and cisplatin resistance in osteosarcoma is established, highlighting the A1BG/NAMPT/PARP1 axis as a critical driver." (PMID 40560034, 2025). "In present study, Alpha 1-B glycoprotein and Serpin family A member 1 were more abundant in cats presenting obesity in comparison with normal-weight cats." (PMID 39795034, 2025).
pancreatic cancer (3 papers, 2008 to 2012). "A1BG was over-expressed in the cytoplasma of malignant epithelia in 86.3% of pancreatic cancer tissues, significantly higher than that in normal pancreas tissues (p < 0.01)." (PMID 18706098, 2008). "Of the identified differently expressed proteins, three up-regulated proteins in pancreatic cancer juice, matrix metalloproteinase-9 (MMP-9), oncogene DJ1 (DJ-1) and alpha-1B-glycoprotein precursor (A1BG), were selected for validation by Western blot and immunohistochemistry." (PMID 18706098, 2008).
rheumatoid arthritis (3 papers, 2016 to 2024). A chronic, systemic autoimmune disorder characterized by inflammation in the synovial membranes and articular surfaces. "FGG has additionally been reported to be expressed at higher levels in rheumatoid arthritis synovial fluid, something that has also been shown for Alpha-1-B Glycoprotein (A1BG), although little else is known about A1BG function." (PMID 30770760, 2019).
Cirrhosis (2 papers, 2020 to 2024). A chronic disorder of the liver in which liver tissue becomes scarred and is partially replaced by regenerative nodules and fibrotic tissue resulting in loss of liver function. "Other significantly downregulated genes by proglumide have been implicated as biomarkers in the progression to cirrhosis, such as A1BG (that codes for Alpha-1-B Glycoprotein; 43), Ppbp (that codes for proplatelet basic protein; 44), and CDC6 (Cell Division Cycle 6; 45)." (PMID 38252699, 2024).
Autoimmunity (1 paper, 2025). The occurrence of an immune reaction against the organism's own cells or tissues. "Among these is alpha-1B glycoprotein (A1BG), a recognized marker for autoimmunity and cancer, whose induction in post-ESWL samples may be due to early and specific alterations in urinary glycoprotein excretion, as found in diabetic nephropathy." (PMID 40427671, 2025).
cholangiocarcinoma (1 paper, 2025). A carcinoma that arises from the intrahepatic biliary tree (intrahepatic cholangiocarcinoma) or from the junction, or adjacent to the junction, of the right and left hepatic ducts (hilar cholangiocarcinoma). "A1BG, a secreted glycoprotein often overexpressed in cancer, has been linked to poor outcomes in cholangiocarcinoma; however, its role in osteosarcoma chemoresistance remains unknown." (PMID 40560034, 2025).
chronic bronchitis (1 paper, 2025). A type of chronic obstructive pulmonary disease characterized by chronic inflammation in the bronchial tree that results in edema, mucus production, obstruction, and reduced airflow to and from the lung alveoli. "In addition, its implication in the immune system function was suggested as Alpha 1-B glycoprotein was increased in patients with chronic bronchitis." (PMID 39795034, 2025).
colitis (1 paper, 2019). Inflammation of the colon. "Of note, alpha-1-B glycoprotein (A1BG) was also decreased, whereas haptoglobin (HP), pregnancy zone protein (PZP), and hemopexin (HPX) were increased throughout the colitis progression in IL-10−/− mice." (PMID 30774653, 2019).
COVID-19 (1 paper, 2023). A disease caused by infection with severe acute respiratory syndrome coronavirus 2. "Other proteins that could potentially be employed in therapies against COVID-19 but that so far have not been associated with the disease are CD5L, VDBP, A1BG, C4BPA, PGLYRP2, SERPINC1, and APOH." (PMID 37371071, 2023). "In addition, other proteins that could be employed in therapies against COVID-19 but that so far have not been associated with the disease are CD5L, VDBP, A1BG, C4BPA, PGLYRP2, SERPINC1, and APOH." (PMID 37371071, 2023).
dilated cardiomyopathy (1 paper, 2025). Cardiomyopathy which is characterized by dilation and contractile dysfunction of the left and right ventricles. "Functional network analyses of the cardiac interactomes of female and male A1BG reveal that A1BG interacts with different sets of proteins based on sex, suggesting that these interactions are crucial for the sex-specific roles of A1BG in cardiac function and dilated cardiomyopathy." (PMID 40270023, 2025).
Jaundice (1 paper, 2023). Yellow pigmentation of the skin due to bilirubin, which in turn is the result of increased bilirubin concentration in the bloodstream. "Tonack and collaborators have also looked for potential plasma biomarkers for PDAC and found some candidates, but they are associated with jaundice, showing the highest sensitivity of ITIH3, C5, A1BG, PIGR, and Reg3A in this condition." (PMID 37628784, 2023).
malaria (1 paper, 2018). Malaria is a serious and sometimes fatal disease caused by a parasite that commonly infects a certain type of mosquito which feeds on humans. "Other cellular proteins correlating with PF3D7_1460800 included alpha-1-B glycoprotein (A1BG), complement factor B (CFB), and CD14, which were previously reported to be differentially expressed in malaria patients." (PMID 29425228, 2018).
renal failure (1 paper, 2024). "Further, the most differentially abundant proteins found to be associated with renal failure were serotransferrin (TF), alpha-trypsin 1 (SERPINA1), alpha-1B-glycoprotein (A1BG), and NHL repeat-containing protein 3 (NHLRC3)." (PMID 38536893, 2024).
Sepsis (1 paper, 2013). Sepsis is defined as life-threatening organ dysfunction caused by a dysregulated host response to infection. "For sepsis prognosis, five proteins were significantly up-regulated: selenium binding protein-1, heparan sulfate proteoglycan-2, alpha-1-B glycoprotein, haptoglobin, and lipocalin; two proteins were significantly down-regulated: lysosome-associated membrane proteins-1 and dipeptidyl peptidase-4." (PMID 23372690, 2013).
cancer (12 papers, 2008 to 2025). A tumor composed of atypical neoplastic, often pleomorphic cells that invade other tissues. "A1BG may be a cancer-associated gene and a novel tumor marker for cancer." (PMID 25435926, 2015). "Proteomic analysis identified A1BG, a secreted glycoprotein overexpressed in various cancers, as a potential mediator of adipocyte‐induced cisplatin resistance." (PMID 40560034, 2025). "In this study, we first identified and confirmed A1BG as an elevated protein in pancreatic juice and cancer tissues of PDAC." (PMID 18706098, 2008). "CRISP3 is an abundant protein of the human seminal plasma and interacts with alpha-1-B glycoprotein (A1BG), a human plasma glycoprotein that is upregulated in different types of cancers." (PMID 39433128, 2024). "The cancer-promoting proteins (NCBP2, AMD, MER34, ENC1, and COA4) were suppressed, while the secretory glycoprotein (A1BG) and ROS-reducing protein (ASB6) were overexpressed in the treatment group." (PMID 35818360, 2022). "The volcano plot revealed that the cancer-promoting proteins (NCBP2, AMD, MER34, ENC1, and COA4) were down-regulated, while the secretory glycoprotein (A1BG) and ROS-reducing protein (ASB6) were up-regulated in the treatment group." (PMID 35818360, 2022). "Other markers (Alpha-1-acid glycoprotein 2 (ORM2), Alpha-1B-glycoprotein (A1BG), Haptoglobin (HP), and Leucine-rich alpha-2-glycoprotein (LRG1), etc.)were found to create an ambiguous core involved in cancer development but also to exactly promote tumor progression in the early stages." (PMID 32023884, 2020).
tumor (9 papers, 2008 to 2025). "Both peptides at m/z 867.513 and 1166.611, respectively assigned to FNDC1 and A1BG proteins, were significantly more intense in PD tumor over control regions (p = 0.0006 for m/z 867.513 and p = 0.0395 for m/z 1166.611)." (PMID 34885011, 2021). "Based on our mass spectrometry data, A1BG and LRG1 were among the most markedly up-regulated proteins in the urine samples from tumor-bearing mice." (PMID 26133466, 2015).
cardiovascular diseases (2 papers, 2024 to 2025). "As estrogen protects against various cardiovascular diseases, including DCM, by influencing cardiac metabolism, gene expression, and structural integrity, we propose that A1BG acts downstream or in parallel to estrogen signaling." (PMID 39070637, 2024).
infection (1 paper, 2021). The state of being infected such as from the introduction of a foreign agent such as serum, vaccine, antigenic substance or organism. "Only three proteins, Itih2, A1bg, and Kng2, were significantly increased during infection with the WT strain only." (PMID 34721327, 2021).
A1BG also shares sentences with these, for which no sentence is quoted: gastric cancer (2 papers); liver cancer (2); nephrotic syndrome (2); Arthritis (1); benign prostatic hyperplasia (1); cervical intraepithelial neoplasia (1); diabetes (1); diabetic nephropathy (1); glomerulosclerosis (1); hepatocellular carcinoma (1); Insulin resistance (1); melanoma (1); meningioma (1); osteosarcoma (1); steroid-resistant nephrotic syndrome (1); Stroke (1).